MYH6 (myosin heavy chain 6)
Description:
Muscle contraction.
Synonyms: MYHCA; ASD3; CMD1EE; CMH14; MYHC; SSS3; alpha-MHC
Tractability: Small molecule: an approved drug acts on it. PROTAC: ubiquitination databases record sites on it.
Gene: Protein-coding gene on chromosome 14 (23,381,576 to 23,408,945, reverse strand). Ensembl gene ENSG00000197616.
Subcellular location: Cytoplasm, myofibril
Subcellular location (Human Protein Atlas): Focal adhesion sites
Pathways (Reactome):
Muscle contraction: Striated Muscle Contraction
Gene Ontology:
Molecular function: microfilament motor activity; protein kinase binding; actin filament binding; myosin phosphatase activity; ATP binding; cytoskeletal motor activity
Biological process: adult heart development; ATP metabolic process; atrial cardiac muscle tissue morphogenesis; muscle contraction; muscle filament sliding; regulation of heart rate; regulation of the force of heart contraction; striated muscle contraction; ventricular cardiac muscle tissue morphogenesis; cardiac muscle cell development; cardiac muscle contraction; in utero embryonic development; myofibril assembly; regulation of blood pressure; regulation of heart contraction; sarcomere organization; visceral muscle development; muscle system process
Cellular component: cytoplasm; cytosol; muscle myosin complex; myofibril; myosin complex; myosin filament; myosin II complex; sarcomere; stress fiber; Z disc
Genetic constraint (gnomAD): Loss-of-function variants: 125 observed, 228.88 expected, observed/expected ratio (o/e) 0.55, 90% interval 0.47 to 0.63. The upper end of that interval is the gene's LOEUF score, 0.63, which puts it in group 2 of 6, group 1 being the genes least tolerant of losing a copy. Missense variants: 2,039 observed, 2,620 expected, observed/expected ratio (o/e) 0.78, 90% interval 0.75 to 0.81. Synonymous variants: 978 observed, 1,044.1 expected, observed/expected ratio (o/e) 0.94, 90% interval 0.89 to 0.99.
Gene-disease validity (ClinGen):
ClinGen rates the evidence that MYH6 causes each of these diseases.
MYH-6 related congenital heart defects (autosomal dominant): Definitive. A heart disease that is present at birth that is caused by a variation in MYH-6.
dilated cardiomyopathy 1EE (autosomal dominant): Limited. Any familial isolated dilated cardiomyopathy in which the cause of the disease is a mutation in the MYH6 gene.
hypertrophic cardiomyopathy (autosomal dominant): Disputed. A condition in which the myocardium is hypertrophied without an obvious cause.
Homologues: Orthologues: chimpanzee MYH6 (99% identical), guinea pig MYH6 (97% identical), mouse Myh6 (97% identical), rat Myh6 (97% identical), pig MYH6 (96% identical), tropical clawed frog myh6 (89% identical), zebrafish smyhc3 (86% identical), zebrafish myh7 (86% identical), zebrafish smyhc2 (85% identical), zebrafish smyhc1 (85% identical). Paralogues in human: MYH7 (93% identical), MYH1 (81% identical), MYH2 (81% identical), MYH4 (80% identical), MYH8 (80% identical), MYH3 (79% identical), MYH13 (77% identical), MYH7B (68% identical), MYH15 (62% identical), MYH9 (42% identical), MYH10 (42% identical), MYH11 (42% identical), and 32 more.
Diseases named in the same sentence as MYH6 in open-access papers:
MYH6 is named in the same sentence as 142 diseases in open-access papers, as found by Europe PMC text mining. Sharing a sentence is not in itself a finding about the gene and the disease. The quoted sentences say what the papers report.
cardiac hypertrophy (73 papers, 2009 to 2025). "The MYH7 R453C mutant not only developed cardiac hypertrophy remodelling, but also severe pathological fibrosis and loss of cardiomyocytes, while the MYH6 R453C mutant showed milder HCM characteristics." (PMID 38862020, 2024). "The downregulation of MYH6 which encodes for myosin heavy chain 6 was expected given the cardiac hypertrophy." (PMID 39546298, 2024). "Reports indicate THRB's regulation of genes linked to myocardial hypertrophy, including Myh6, Adrb1 and Atp2a2,28, 29 highlighting its role in myocardial remodelling and explaining the downregulation of HINT2 expression." (PMID 38546629, 2024). "MYH7 is a hallmark of cardiac hypertrophy, and the switch in MYH6:MYH7 expression ratio is linked to cardiac hypertrophy and heart failure." (PMID 28752208, 2017). "First, the observed changes of Myh6 and Adam12-l mRNA expression are consistent with events that underlie cardiac remodeling during cardiovascular pathophysiologies such as cardiac hypertrophy." (PMID 24586524, 2014). "In addition, upregulated β-myosin expression (β-MHC, encoded by MYH7), accompany with downregulated α-myosin expression (α-MHC, encoded by MYH6) is a sensitive indicator of cardiac hypertrophy." (PMID 33195237, 2020). "To further investigate whether this cardiac histological change was physiological or pathological, we examined the expression of four genes associated with pathological cardiac hypertrophy, including Myosin heavy chain 6 (Myh6), Natriuretic Peptide A (Nppa), Nppb, and Myh7." (PMID 41460785, 2025). "We detected an increase in biomarker mRNA expression indicative of cardiac hypertrophy, specifically Myh6 and Nppa, while the levels of Myh7 and Nppb remained unchanged." (PMID 40463063, 2025). "The ratio of MYH7 to MYH6 was also upregulated in mutant cells, which was considered as cardiac hypertrophy marker." (PMID 39981966, 2025). "Here, we generated transgenic MYH7 R453C and MYH6 R453C piglets and found both developed typical cardiac hypertrophy." (PMID 38862020, 2024). "A lower expression of Nppa, Nppb, a lower Myh7/Myh6 RNA ratio, and a reduced CM cross-sectional area confirmed blunted cardiac hypertrophy in Gadlor-KO animals compared with WT littermates after TAC." (PMID 39281699, 2024). "The re-expression of foetal Myh7 with concomitant down-regulation of Myh6 is a well-known characteristic of pathological cardiac hypertrophy in rodents." (PMID 39206703, 2024). "AAV9-mediated overexpression of miR-1 reduced several markers of cardiac hypertrophy including MYH6 and blunted adverse cardiac remodeling through maintenance of calcium homeostasis regulation by sarco/endoplasmic reticulum Ca2+ (Serca)." (PMID 38132140, 2023). "The results showed that with the continuous maturation of cardiomyocytes, the MYH7/MYH6 ratio of KO hiPSC-CMs was gradually increased compared with WT hiPSC-CMs, and KO hiPSC-CMs showed a pathological phenotype of myocardial hypertrophy." (PMID 38072986, 2023). "For example, miR-208 and its host gene MYH6 are involved in the occurrence of myocardial hypertrophy and fibrosis." (PMID 37978168, 2023). "Expressions of cardiac hypertrophy marker genes Myh7 and Myh6 were dysregulated upon MI surgery and partially restored by CPX treatment." (PMID 36826549, 2023). "mRNA expression of cardiac hypertrophy marker genes Nppa, Nppb, Myh6, and Myh7 was massively enhanced compared with genes in control mice on P25." (PMID 35167494, 2022). "The most dysregulated cardiac hypertrophy-related gene in human myectomy tissue was MYH6 (alpha myosin heavy chain, log2FC: − 1.91)." (PMID 34162896, 2021). "Nonetheless, upon heart failure/heart hypertrophy, a switch in the expression pattern, leading to an increased/a more pronounced expression of myh6/β-MHC, occurs." (PMID 34201741, 2021). "Reduced hypertrophic remodeling in aYAP+IR was further supported by measurement of Myh6 and Nppa, which are commonly down-regulated and up-regulated, respectively, in cardiac hypertrophy." (PMID 31843959, 2020).
cardiac hypertrophy (continued). "Quantitative PCR analysis of message levels of pro-hypertrophic genes, including Nppa, Nppb, and Myh6, confirmed that cardiac hypertrophy was ameliorated in the ecKO mice compared to the WT mice." (PMID 32733885, 2020). "mRNA expression analysis revealed activation of molecular profiles of cardiac hypertrophy with increased fetal cardiac gene expression, i.e., Nppa, Nppb, Myh7, and decreased Myh6 expression." (PMID 33203971, 2020). "In order to assign a cell-specific role for MRTF-A in the pathogenesis of cardiac hypertrophy, MRTF-A was specifically deleted in cardiomyocytes by removing the floxed Mrtfa allele with a Myh6-Cre driver." (PMID 33015041, 2020). "Genetic variants of MYH6, TNNT2 and TPM1, have been found to be associated with hypoplastic left heart, cardiac hypertrophy and DCM, respectively." (PMID 32423033, 2020). "Gene expression of cardiac hypertrophy related genes such as MYH6, TNNT2, NPPA, and NPPB was modestly induced in ISO-treated WT hESC-CMs, but was found to be markedly elevated in MLP KO hESC-CMs." (PMID 31406109, 2019). "Further, in cardiac hypertrophy an elevation of Myh7 can serve as an early and sensitive marker and recently downregulation of Myh6 expression in human hearts was observed, too." (PMID 30564194, 2018). "Cardiac hypertrophy was also evidenced by the gradual increase in Myh7 and decrease in Myh6 at mRNA level." (PMID 27731386, 2016). "To elaborate on the DNA methylation array results, we selected several DMRs at different gene loci related to cardiac hypertrophy including Mef2c, Tnnt2, Myh6, Myh7, and Gata4 and body weight Ins2 for bisulfite sequencing." (PMID 24475304, 2014). "Analysis of a more specific ontology, cardiac hypertrophy – NF-AT signaling, revealed similar genes as the general hypertrophic cardiomyopathy ontology such as Myh6, Myh7, Tnnt2, Tnni3, and Actc1." (PMID 24475304, 2014). "We also analyzed myosin heavy chain alpha (Myh6) and myosin heavy chain beta (Myh7), as their expression is altered during cardiac hypertrophy." (PMID 24475304, 2014). "In parallel, cardiac hypertrophy correlates withdownregulation of adult α-myosin heavy chain (MYH6) and sarco/endoplasmicreticulum calcium ATPase-2 (SERCA2)." (PMID 20228935, 2009). "However, cardiomyocyte-specific Rac1 knockin mice (Rac1cKI/cKI; Myh6-Cre) exhibited significantly exacerbated cardiac hypertrophy in response to AngII, indicating hypersensitivity to AngII-induced cardiac hypertrophy in the absence of Rac1 S-palmitoylation." (PMID 40924486, 2025). "The ratio of MYH7 to MYH6 was considered as cardiac hypertrophy marker." (PMID 39981966, 2025). "Cardiac hypertrophy was assessed by measuring the ratio of hypertrophy genes Myh7: Myh6." (PMID 39062999, 2024). "Moreover, cardiomyocyte-specific monocarboxylate transporter 1 (MCT1)-knockout mice (MCT1fl/fl: Myh6-Cre) exhibited blocked shuttling of lactate from CFs to cardiomyocytes and attenuated Ang II-induced cardiac hypertrophy." (PMID 37580825, 2023). "It appears that our strain (5-month-old Prdm16flox/flox; Myh6-Cre) progresses to cardiac hypertrophy earlier than 9-month-old Prdm16flox/flox; Mesp1-Cre mice, consistent with the other conditional strain (Prdm16flox/flox; αMHCMerCreMer/+) developing cardiac hypertrophy as early as age 3 months." (PMID 35862303, 2022). "SIRT3 knockout mice exhibited a more severe cardiac hypertrophy and fibrosis after Ang II infusion, and these mice also exhibited increased cardiomyocyte size with an upregulation of MYH6 expression, increased interstitial and perivascular fibrosis, and upregulation of α‐SMA expression." (PMID 34180125, 2021). "In addition, gene expression levels of cardiac hypertrophy markers Myh7/Myh6, Nppa, and Nppb were significantly lower in the hearts from Mkp-5-/- mice as compared with Mkp-5+/+ controls at 4 weeks after TAC." (PMID 34992607, 2021).
cardiac hypertrophy (continued). "In addition, GLA-null CMs were characterized by shifted balance between α- and β-cardiac myosin heavy chain (MYH6/MYH7 ratio) expression, which is a common response to cardiac injury and a hallmark of cardiac hypertrophy." (PMID 30965672, 2019). "Additionally, MYH6 mutations can lead to a spectrum of dilated and hypertrophic phenotypic changes, ranging from DCM to HCM, including myocardial hypertrophy progressing to dilation and systolic dysfunction, as well as severe adverse outcomes in DCM patients, such as sudden death and heart failure." (PMID 40406620, 2025). "Whether the increased Myh6 and Myh7 expression in vitro and in vivo results from increased occupancy of the promoters of these genes by the P-TEFb complex or is simply reflecting cardiac hypertrophy remains an open question." (PMID 27270731, 2016). "Cumulative and average daily running distance was similar between control Myh6‐MCM and Mc1r‐cKO mice, indicating equal stimulus for physiological cardiac hypertrophy." (PMID 39921516, 2025). "To test for a regulatory role of MC5-R in cardiac hypertrophy, we engineered a tamoxifen-inducible cardiomyocyte-specific MC5-R KO mice (Mc5r-cKO) by crossing Mc5rfl/fl mice with Myh6-MCM transgenic mice." (PMID 38454158, 2024). "The protein and mRNA levels of the hypertrophic marker ANP were increased while MYH6 was decreased, demonstrating that HFD-induced cardiac hypertrophy model was successfully established." (PMID 39294131, 2024). "Consistent with cardiomyocyte hypertrophy, qPCR showed increased mRNA expression of cardiac hypertrophy markers (ANP, BNP and MYH7) and decreased mRNA expression of MYH6 in PD‐iCMs." (PMID 37916452, 2024). "Both groups of mice developed a comparable degree of cardiac hypertrophy in response to TAC, as shown by similarly enhanced HW/TL ratio, embryonic gene expression (decrease in Myh6 and Atp2a2, increase in Myh7 and Acta1 mRNA) and cardiomyocyte size." (PMID 35013221, 2022). "The expression of TGF-β and p-Smad3 reduced after QYYY treatment, as well as MYH7 and MYH7/MYH6, which demonstrated QYYY granules can downregulate the key genes involved in cardiac fibrosis and cardiac hypertrophy." (PMID 34484396, 2021). "Transcription of myosin heavy chain α (MYH6) and β (MYH7), defined markers for myocardial hypertrophy, resembled this predominant obesity‐induced effect on cardiac remodelling." (PMID 31368189, 2019). "Subsequent studies indicate that cardiac hypertrophy usually accompanies upregulation of BNP and MYH7 and/or downregulation of MYH6 expression levels." (PMID 28479925, 2017). "However, because MYH6 is mainly expressed in the atrial muscles and not in the ventricular muscles in human adult hearts, pathological role of the MYH6 mutation in cardiac hypertrophy in this case might be less significant than the MYBPC3 mutation." (PMID 27160240, 2016). "Cardiac fetal genes (NPPA, NPPB, MYH6, MYH7 and ACTA1) are usually only expressed during fetal life and re-expression of these genes in adult life is an indicator of pathologic cardiac hypertrophy." (PMID 25051449, 2014). "Control mice (either Myh6-Cre alone or Rac1cKI/cKI mice without Myh6-Cre) consistently displayed modest increases in cardiac hypertrophy in response to AngII, as expected." (PMID 40924486, 2025). "Although these results indicate that the transgene per se does not promote cardiac hypertrophy or lifespan at the timepoints analysed, we cannot fully exclude cardiotoxic off-target effects of Cre recombinase under the Myh6 promoter." (PMID 36880401, 2023). "Therefore, the study of these two MYHC molecules and their genes, MYH6 and MYH7, will give us further insights into cardiac hypertrophy and potentially help us improve the diagnosis and treatment of various other cardiomyopathies." (PMID 36157891, 2022).
cardiac hypertrophy (continued). "In addition, overexpression of FST promoted cardiac hypertrophy with an unchanged expression of atrial natriuretic peptide (ANP) and the ratio of myosin heavy chain-β/myosin heavy chain-α (MYH7/MYH6)." (PMID 34385917, 2021). "There was also an increase in the expression of cardiac hypertrophy molecular markers, including myosin heavy chain 7 (Myh7 or β-myosin heavy chain, β-Mhc), and natriuretic peptide B (Nppb or Bnp), in KO mice compared with WT animals, although Myh6 (α-Mhc) was not modified." (PMID 40301189, 2025). "Also, compared with control, one μM WIN did not increase MYH6 and MYH7 mRNA levels, genes that, when upregulated, may indicate cardiac hypertrophy in vitro." (PMID 34707939, 2021).
heart failure (58 papers, 2012 to 2025). Inability of the heart to pump blood at an adequate rate to meet tissue metabolic requirements. "In vivo mechanistic studies have demonstrated significant bradycardia in MYH6 knockout models while another study found that low expression levels of MYH6 are associated with ischemic cardiomyopathies and heart failure." (PMID 40565507, 2025). "Lactylation of the alpha-myosin heavy chain (alpha-MHC) lysine 1897 site encoded by the Myh6 gene is reduced in mice and heart failure patients." (PMID 38668345, 2024). "YAP is one of the essential terminal effectors of the Hippo-YAP pathway, and knocking out YAP with the MDS Myh6-Cre causes heart failure and premature death (a median lifespan between 10 and 11 weeks)." (PMID 39323506, 2024). "Cardiac toxicity at a cumulative dose of 12 mg/kg (3 mg/kg/week for 4 weeks) was confirmed by histopathological lesions and altered expression of genomic indicators associated to contraction performance (Myh6, Myh7) and heart failure (Ankrd1/CARP, Nppb)." (PMID 22859947, 2012). "Increasing the Myh7/Myh6 ratio by overexpression of Myh7 has been shown to cause heart failure." (PMID 33260869, 2020). "To further validate the findings that lack of PIMT expression is solely responsible for the heart abnormalities and associated heart failure observed in csPIMT−/− mice, we used tamoxifen-inducible heart-specific Cre (Myh6-MCM)/PIMTfl/fl mouse model (TmcsPIMT−/−)." (PMID 29772707, 2018). "To firmly establish that the lack of Med1 expression is solely responsible for all the heart abnormalities and the associated heart failure observed in csMed1-/- mice, we used tamoxifen-inducible heart-specific Cre (Myh6-MCM)/Med1fl/fl mouse model (TmcsMed1-/-)." (PMID 27548259, 2016). "Cardiac hypertrophy and heart failure causes MYH6 downregulation." (PMID 26347658, 2015). "Heart failure-associated fetal gene program is also characterized by upregulation of β-MyHC (Myh7), the dominant isoform of myosin heavy chain in the fetal cardiomyocytes, and a down regulation of α-MyHC (Myh6), the dominant isoform in the adult cardiomyocytes." (PMID 30811446, 2019). "External dataset validation and analyses indicate that MYH6 is lowly expressed in myocardial tissues of heart failure patients, while RT-qPCR results show that MYH6 is highly expressed in the plasma of HF patients." (PMID 40406620, 2025). "The results showed that, compared to normal samples, HMGN2, HTRA1, LTBP2, and MFAP4 were significantly upregulated in heart failure, while MYH6 was downregulated (p < 0.001)." (PMID 40406620, 2025). "A reduced MYH6/MYH7 gene expression ratio is a well-established molecular hallmark of cardiomyopathy and heart failure." (PMID 41295372, 2025). "Myh6 and Myh7 are genes that encode the α- and β-myosin heavy chain (MHC), respectively, and can serve as a marker for heart failure-related sarcomeric remodelling." (PMID 40517248, 2025). "Myh6 (α-myosin heavy chain) and Myh7 (β-myosin heavy chain) are differentially regulated in heart failure, and mRNA levels for these genes were oppositely modulated by the TM54 transgene and AAV9sc.PBD treatment." (PMID 38572067, 2024). "These EVs contributed to preventing maladaptive remodeling, inhibiting the onset of fibrosis, and decreasing the expression of heart failure molecular indicators (such as myosin heavy chain isoforms Myh6/Myh7 ratio)." (PMID 38892376, 2024). "Transcript levels of several secreted biomarkers of heart failure were quantified by RT-PCR and were increased in the Myh6-McmTam:DspF/F cardiac myocytes." (PMID 36818425, 2023). "In 3 months old mice, Western blot analysis showed that Vps4a protein levels were significantly decreased in Vps4afl/fl Myh6 mice compared to Vps4afl/fl mice, while the expressions of markers for heart failure, such as p-AKT and Myh7, increased." (PMID 37445978, 2023).